EGFR (epidermal growth factor receptor)
Diseases named in the same sentence as EGFR in open-access papers (continued):
Sharing a sentence is not in itself a finding about the gene and the disease.
tumor (continued). "While two responders had documented tumor EGFR mutations, one had wild type disease and the rest insufficient tissue for genotyping." (PMID 29050231, 2017). "Amplified expression of EGFR and of its mutated variant v3, has been extensively studied as a possible target for anti-tumor therapy, although clinical trials focused on this treatment approach have so far yielded unsatisfactory results." (PMID 28587680, 2017). "PFS is the primary end point, and assessment of PFS is the secondary end points which based on T790M mutation status before treatment and the common EGFR mutation (exon 19 deletion or L858R) tested by circulating tumor DNA." (PMID 29088904, 2017). "We have demonstrated that in the NSCLC cell lines, A549, SPC-A1 and HCC827 (EGFR-mutated), miR-34a acted as a tumor suppressor through the direct targeting of EGFR." (PMID 28825720, 2017). "Unfortunately, despite dramatic initial response to the targeted therapy, EGFR mutation-positive patients usually suffer from the development of drug resistance and tumor progression after 9 to 14 months of treatment." (PMID 28881827, 2017). "Here the authors show that this protein modulates trapping of the epidermal growth factor receptor at the cell surface, causing persistent signalling activation and tumour progression." (PMID 28416796, 2017). "Due to the complexity of EMT and genetic mutations of EGFR associated with TKI resistance in heterogeneous subpopulations of a tumor, the roles of EMT and EGFR mutations in TKI resistance should be further investigated." (PMID 28683123, 2017). "It should be noted that most of the other techniques used for EGFR mutations detection (except ddPCR) require a percentage of tumor cells at least greater than 20%." (PMID 29262544, 2017). "In this subgroup, EGFR protein overexpression was found to be significantly associated with poor differentiation of the tumor cells (p = 0.003) and lymph node metastasis, especially extra-capsular spread (ECS) (p = 0.03)." (PMID 28694429, 2017). "This mutation deletes exons 2 to 7 of the EGFR gene, leading to low-level constitutive signaling that can drive tumor progression." (PMID 28970798, 2017). "EGFR gene mutation results should be obtained quickly, given the rapid tumor progression and the availability of effective targeted therapy." (PMID 29262544, 2017). "In the clinical study, EGFR mutations were detected in 45.9% (50/109) of the plasma samples and in 56.9% (62/109) of the matched tumor tissue samples." (PMID 28829813, 2017). "We also demonstrated a high sensitivity of this method, with the use of different dilutions of DNA from tumor cell lines containing mutations in the EGFR gene." (PMID 28827701, 2017). "Epidermal growth factor receptor (EGFR) mutation testing in tumor tissue is now a common practice in selecting non-small cell lung cancer (NSCLC) patients for EGFR tyrosine kinase inhibitor (TKI) treatment." (PMID 28207548, 2017). "EGFR overexpression in BC is associated with large tumor size, poor differentiation, and poor clinical outcomes." (PMID 29267323, 2017). "Out of the 109 patients, 42 (including 41 newly diagnosed and 1 recurrent disease after surgery) had measurable tumors and positive EGFR mutation in tumor tissues and received Gefitinib or Icotinib as first-line treatment." (PMID 28829813, 2017). "The affibody‐presenting mC‐DL‐HBVC was effectively endocytosed by EGFR‐overexpressing tumor cells and less susceptible to intracellular degradation." (PMID 28546913, 2017). "Five patients in our cohort whose tumor harbored EGFR exon 20 mutation (four with duplication and one insertion) all showed no response to erlotinib." (PMID 29232915, 2017). "The EGFR is frequently overexpressed or mutated in various cancers leading to aberrant signaling and tumor growth." (PMID 27956147, 2017).
tumor (continued). "Of interest, additional analyses of ASSESS study data found that detection of EGFR mutations in plasma was significantly more likely when patients had a higher metastatic tumor burden and distant metastases." (PMID 27980215, 2017). "Taken together, our data indicate that the proximity of macrophages to tumour cells was positively associated with EGFR activity, and this association persists despite the inhibition of EGFR activity by a TKI." (PMID 28166195, 2017). "In EC, epidermal growth factor receptor (EGFR) overexpression is common, and is associated with deep myometrial invasion, tumor grade, and a poor prognosis." (PMID 29214032, 2017). "An EGFR activating mutation (Del19, p.L858R or p.L861Q) was found in tumor DNA of 50 patients (38 Del19, 10 p.L858R and 2 p.L861Q)." (PMID 28829811, 2017). "Tumor response, progression-free survival, and overall survival according to different blood EGFR mutation testing methods will be evaluated and compared." (PMID 28207548, 2017). "For each patient sample, the expected mutation status was determined in the primary tumor DNA via conventional Cycleave assays or the SARMS assay for EGFR or KRAS mutations, respectively." (PMID 28625519, 2017). "Univariate analyses of patients with EGFR mutations in cfDNA identified the L858R mutation in tumor tissue or in cfDNA as a marker of shorter OS (hazard ratio, 2.70; P < .001) and PFS (HR, 2.04 [95% CI, 1.20 to 3.48]; P = .008)." (PMID 28099915, 2017). "In this work, the high sensitivity and accuracy of multiplex picodroplet dPCR enabled detection and quantification of 2 EGFR-activating mutant alleles and a rare EGFR-TKI resistance allele in NSCLC tumor samples." (PMID 28625519, 2017). "Patients with EGFR-positive tumors are characterized by lower survival rates and are associated with the risk of higher tumor recurrence." (PMID 28270211, 2017). "In the bone microenvironment, active EGFR signal pathway in tumor cells was associated with angiogenesis and cell proliferation." (PMID 29113396, 2017). "For EGFR mutation testing, 19 studies used tumor tissue samples, six studies cytological materials and three studies blood samples, with four studies using more than one type of samples and two not specifying the specimen types." (PMID 28938658, 2017). "Univariate analysis was performed on the EGFR mutation status in plasma cfDNA samples and tumor tissues in accordance with gender, age, smoking history, pathological type, disease staging, and plasma cfDNA specimen collection time." (PMID 28052016, 2017). "To date, three generations of EGFR TKIs have been developed, and the third-generation molecular targeted drug WZ4002 exhibits high activity against tumor cells harboring EGFR with the T790M mutation." (PMID 27713133, 2017). "In GBM cells with EGFR mutation, which is occurring in large proportion of patients, miR-9 is identified as a tumor suppressor which is regulated by FOXP1." (PMID 28868238, 2017). "In clinical practice, EGFR mutations are routinely detected using DNA extracted from primary or metastatic tumour tissue obtained during tumour biopsy or resection, which is typically formalin fixed and paraffin embedded (FFPE)." (PMID 28006816, 2017). "Follow-up data from the three patients who benefited from EGFR-TKI treatment demonstrated that either cfDNA or tumor-tissue EGFR mutation positivity can be treated as a true positive and can predict the efficacy of EGFR-TKI treatment." (PMID 28052016, 2017). "Currently, the tumor tissue has been used as the standard sample type for EGFR mutation detection in the clinical practice, but it has several limitations." (PMID 28829813, 2017). "The current therapeutic approaches mainly target the molecular mechanisms of tumor cell growth caused by the aberrant activity of epidermal growth factor receptor (EGFR)." (PMID 28210267, 2017). "The tumor enhancing effects caused by EGFR-sensitizing mutations has impact on the activation of downstream signaling pathway." (PMID 29050366, 2017).
tumor (continued). "CTCs can be used for various clinical applications as previously reported and they have advantages over circulating tumor-derived DNA (ctDNA), which is currently approved for EGFR mutation testing." (PMID 28640869, 2017). "In the present study, we demonstrated the changes of EGFR mutation of 45 NSCLC patients through AMPS PCR technology with tumor tissues, and monitored the EGFR mutation status by peripheral blood ctDNA." (PMID 28333951, 2017). "Preclinical data from mouse xenograft models suggested that pulsed gefitinib (another EGFR TKI) before paclitaxel caused significantly more tumor regression than continuous gefitinib dosing in combination with paclitaxel." (PMID 27853997, 2017). "Improvements in clinical outcomes with afatinib vs chemotherapy in both LL3 and LL6, particularly in patients with tumours harbouring common EGFR mutations (Del19/L858R), have been previously reported." (PMID 28006816, 2017). "BRAF mutations are present in approximately 2–3% EGFR wild-type tumor also confer intrinsic resistance due to the presence of other somatic mutations in genes encoding signaling molecules." (PMID 29050366, 2017). "Activating and resistance mutations in EGFR can be detected with tissue biopsies or on cytological tumor samples from patients with metastatic NSCLC." (PMID 29125548, 2017). "Among the 215 tumor-tissue specimens, 102 EGFR gene mutations (46.5%) were found in 100 specimens, including 93 cases of Exon 19 del or Exon 21 L858R." (PMID 28052016, 2017). "To evaluate the correlation of circulating mutant DNA levels with tumor dynamics, we analyzed the mutant DNA of 36 patients with EGFR L858R mutation at different time points following surgery." (PMID 28382702, 2017). "EGFR overexpression is associated with poor prognosis, increased tumor growth, metastasis, and resistance to chemotherapy and radiation therapy." (PMID 29190900, 2017). "Previously, EGFR mutation abundance in tumor tissues has been correlated with benefit from TKI treatment for advanced NSCLC." (PMID 28969034, 2017). "These targeted therapies have further developed as a result of advancements in tumour analysis for protein mutations that cause uncontrolled proliferation, such as those in epidermal growth factor receptor (EGFR) and anaplastic lymphoma kinase (ALK)." (PMID 28955400, 2017). "No notable differences were observed based on age, race, smoking status, disease stage, pleural metastases, brain metastases, or original EGFR mutation type in the tumour in either study." (PMID 28006816, 2017). "It occurs first and foremost in advanced tumours that have lost normal regulatory feedback circuits and use mutated EGFR to constitutively drive proliferation and survival." (PMID 28417948, 2017). "Histological grading of the tumor influenced the likelihood of being tested for EGFR-mutational status." (PMID 29100434, 2017). "According to the plasma EGFR mutation status, patients were divided into two subgroups: patients with EGFR mutations detected in both tissue and plasma specimens (T+P+, n=34), and patients with tumor tissue EGFR mutations only (T+P-, n=10)." (PMID 29340107, 2017). "The mutated-EGFR tumor had a significantly shorter MTSBM than the WT-EGFR one did (for all-stage disease, 31.6 months vs. not reached (NR), P of log-rank test = 0.043; for stage IIIB-IV disease, 23.5 months vs. NR, P = 0.017)." (PMID 28881820, 2017). "In the present case, simultaneous intraparenchymal brain and LM arose during afatinib therapy despite extracranial tumor control, which can be partially attributed to EGFR mutation heterogeneity." (PMID 28540256, 2017). "EGFRvIII is a tumor-specific mutation of EGFR, which is expressed highly in various types of cancer." (PMID 28752098, 2017). "In accordance with previously published results, the only statistically significant associations between our subgroups and the presence of EGFR mutations were gender and tumor type." (PMID 28684733, 2017).
tumor (continued). "In previous analyses, the detection rates for EGFR mutation in blood (plasma or serum) cfDNA compared with paired tumour tissue samples have ranged from 31% to 97%." (PMID 28006816, 2017). "The changes on tumor diameter showed the same dynamic pattern as the plasma EGFR mutation abundance." (PMID 28969034, 2017). "EGFR has been identified as an oncogenic driver of NSCLC, especially activating mutations EGFR and its inhibition with specific TKIs can generate dramatic tumor responses." (PMID 28430586, 2017). "A previous study showed that tumor cells harboring either KRAS/BRAF mutations or EGFR amplification were slightly less sensitive to BEZ235 than other cells." (PMID 29296217, 2017). "R193A/K195A mutations also impaired EGFR-stimulated cell proliferation, cell migration, colony formation, tumor growth, GSC self-renewal, p-STAT3 and ID1 expression." (PMID 29129908, 2017). "It was noted that an increased activation of MAPKs was associated with a reduction of EGFR expression and tumor growth." (PMID 28057023, 2017). "For the first time these results show a significant additive effect in the treatment of advanced NSCLC patients by combining the two different treatment concepts of anti-angiogenesis and inhibition of tumor cell proliferation based on EGFR driver mutations." (PMID 28402937, 2017). "Disruptions in epidermal growth factor receptor (EGFR) trafficking has been linked to tumor progression." (PMID 29084952, 2017). "Recently, circulating tumor DNA (ctDNA) has emerged as an alternative DNA source for detecting EGFR mutations." (PMID 28978074, 2017). "Pre-saturation of EGFR in A431 xenografts caused a significant (p < 0.0005) decrease in tumour uptake of both tracers." (PMID 28729680, 2017). "In the multivariate analysis, which was adjusted for age, gender, and tumor stage, smoking remained an independent predictor of a lower EGFR mutation rate (adjusted odds ratio [aOR], 0.38 [95% CI, 0.34–0.42]; P < 0.001)." (PMID 29228697, 2017). "A HER2 exon 20 insertion was recently found in an EGFR-mutant lung tumor with acquired resistance to osimertinib; no additional cancer-associated mutations were found in this tumor." (PMID 29371993, 2017). "Investigators at PLAGH pioneered an EGFR-directed CAR characterized by a shorted promoter in an effort to minimize the risk of on-target/off-tumor recognition and first tested this receptor in humans (NCT01869166)." (PMID 28466386, 2017). "Baseline examination of EGFR mutations was performed in 102 patients using matched tumor tissues and plasma samples." (PMID 29029416, 2017). "Mutations of epidermal growth factor receptor (EGFR) contribute to the growth and metastasis of tumor." (PMID 28460479, 2017). "Independent-Samples T Test was used to compare the differences in SUVmax and serum tumor marker levels between different EGFR mutation statuses." (PMID 28877268, 2017). "Fifteen studies explored the association between EGFR expression and clinicopathologic parameters, such as invasion depth, tumor differentiation, tumor stage, and lymph node metastasis." (PMID 28199988, 2017). "The study showed that ctDNA EGFR mutation testing from urine is a novel way to non-invasively detect the T790M mutations missed in biopsies because of tumor heterogeneity or inadequate sample quality." (PMID 28099915, 2017). "When analysed separately for males and females, the association between EGFR gene amplification and proximal tumours was significant in males (Fisher’s exact test, p = 0.011; OR 3.58, 95 % CI: 1.37–9.36) but not in females." (PMID 27387915, 2016). "The ratios between these factors suggest that a mutation of EGFR increases tumor invasion more than a mutation of MAPK, and a mutation of MAPK increases tumor invasion more than a mutation of AKT." (PMID 28002496, 2016). "A relationship between higher EGFR expression and decreased survival in BC patients has been described as well as an association between EGFR expression and undifferentiated tumor cells." (PMID 27055285, 2016).
tumor (continued). "In about 60% of the patients, resistance to EGFR inhibitors in NSCLC is typically associated with the clonal expansion of tumour cells bearing a T790M ‘gatekeeper’ mutation." (PMID 27350784, 2016). "In many cases, tumor evolution results in secondary EGFR T790M mutations in exon 20 leading to resistance to EGFR TKIs." (PMID 27588476, 2016). "Although, numerous studies have investigated the diagnostic accuracy of cfDNA for detection of EGFR mutations, the concordance rate of EGFR mutations between cfDNA and tumor tissue varies." (PMID 27081078, 2016). "They reported that treatment of the SCC13 cells with GSPs resulted in inhibition of cell invasion which was associated with a reduction in the levels of EGFR in the tumor cells, and a reversal of the EMT process." (PMID 27886147, 2016). "In the case of EGFR, much progress has been made since two landmark studies on NSCLC patients demonstrated that EGFR inhibitors were effective only in tumours harbouring activating mutations in the EGFR gene." (PMID 27350784, 2016). "Correlations between serum tumor marker levels and EGFR mutations as well as survival parameters were analyzed and prognostic factors were identified." (PMID 27623437, 2016). "Five patients had an activating mutation of EGFR (L858R, or exon 19 deletion) in both the primary tumor and the metastasis." (PMID 26968843, 2016). "We demonstrated that TIM-3 was upregulated in CD4 and CD8 T cells from anti-PD-1-resistant EGFR and Kras mutated tumours as compared with untreated tumours." (PMID 26883990, 2016). "The tumor volume of the KRAS mutation patients were larger than those of the EGFR mutation patients (P < 0.05)." (PMID 26739511, 2016). "Collectively, our data demonstrate that the IL-17E/IL-17RB pathway contributes to TNBC resistance to EGFR therapeutics through a loop that amplifies and sustains the phosphorylation of the main EGFR downstream kinases implicated in tumor resistance." (PMID 27462789, 2016). "U251 was chosen to screen EFEMP1 variants for ETSP that retains the parental protein's tumor suppressor function in high proliferating TMC via targeting EGFR and angiogenesis, as demonstrated in our previous studies." (PMID 27713911, 2016). "We examined the function of integrin in regulating GSC tumour phenotypes associated with expressing a dominant-negative form of EGFR (EgfrDN), dERK RNAi (rlRNAi), or zfh-1 in somatic cells." (PMID 26792023, 2016). "As similar with our study, tumor size was associated with the EGFR mutation status in this research." (PMID 27472739, 2016). "The median OS was 24.6 months (95 % CI, 20.7–28.5) in patients with plasma EGFR 19DEL or L859R mutations and 27.0 months (95 % CI, 25.0–29.0)) in patients with these mutations in their tumor tissue." (PMID 27519791, 2016). "To elucidate the underlying mechanisms of miR‐134‐mediated tumour suppression in A549 xenografts, we analysed the expression of miR‐134, EGFR, Ki67 and cleaved PARP in resected A549 xenografts." (PMID 27241841, 2016). "Previously, the IPASS study documented prolonged PFS and better tumor response from gefitinib in EGFR-mutated patients." (PMID 27893423, 2016). "In another study, tumor re-biopsy after progression on rociletinib therapy showed that loss of EGFRT790M plus EGFR amplification and small cell transformation were mechanisms of resistance." (PMID 27912760, 2016). "The use of these compounds has been applied to CRC treatment, in order to selectively inhibit tumor-associated activity of kinases such as EGFR, VEGFR, PDGFR, PI3K and mTOR." (PMID 27286453, 2016). "Soluble c-Met levels > 766 ng/ml before EGFR-TKI treatment were associated with a positive c-Met status of the resistant tumor in 4 of 12 patients (33.3%)." (PMID 27213587, 2016). "Being derived from a driver mutation, targeting mutated EGFR-derived peptides represents a particularly promising immunotherapeutic approach since the tumor very likely cannot lose the mutated EGFR protein." (PMID 28123873, 2016).